KLRG2 (killer cell lectin like receptor G2)
Synonyms: CLEC15B; FLJ44186
Tractability: Antibody: UniProt predicts a signal peptide or a membrane-spanning region.
Gene: Protein-coding gene on chromosome 7 (139,450,625 to 139,483,674, reverse strand). Ensembl gene ENSG00000188883.
Subcellular location: Membrane
Subcellular location (Human Protein Atlas): Nucleoplasm
Gene Ontology:
Cellular component: membrane
Genetic constraint (gnomAD): Loss-of-function variants: 33 observed, 24.17 expected, observed/expected ratio (o/e) 1.37, 90% interval 1.03 to 1.79. The synonymous counts are far from expectation, so gnomAD's model fits this gene poorly and the ratio says little. Missense variants: 607 observed, 416.12 expected, observed/expected ratio (o/e) 1.46, 90% interval 1.36 to 1.56. Synonymous variants: 274 observed, 190.25 expected, observed/expected ratio (o/e) 1.44, 90% interval 1.3 to 1.59.
Homologues: Orthologues: chimpanzee KLRG2 (99% identical), macaque KLRG2 (90% identical), pig KLRG2 (64% identical), dog KLRG2 (60% identical), mouse Klrg2 (57% identical), rat Klrg2 (56% identical), zebrafish si:dkey-26c10.5 (10% identical), Drosophila melanogaster rgn (9% identical), zebrafish si:ch211-170d8.8 (9% identical), zebrafish si:ch211-193e13.5 (7% identical), Caenorhabditis elegans clec-146 (6% identical), Caenorhabditis elegans clec-196 (5% identical). Paralogues in human: CLEC2L (16% identical), KLRG1 (11% identical), OLR1 (11% identical), CLEC12B (10% identical), CLEC7A (10% identical), CLEC12A (10% identical), CLEC2D (10% identical), CLEC9A (10% identical), KLRC1 (10% identical), CD69 (10% identical), KLRC2 (9% identical), KLRK1 (9% identical), and 11 more.
Diseases named in the same sentence as KLRG2 in open-access papers:
KLRG2 is named in the same sentence as 13 diseases in open-access papers, as found by Europe PMC text mining. Sharing a sentence is not in itself a finding about the gene and the disease. The quoted sentences say what the papers report.
bladder cancer (1 paper, 2025). "Pan-cancer analysis utilizing TCGA and GTEx databases revealed significant overexpression of KLRG2 across multiple malignancies, including EC, ovarian cancer, cervical cancer, bladder cancer, breast cancer, esophageal carcinoma, testicular cancer, and lung adenocarcinoma." (PMID 40722666, 2025).
endometrial carcinoma (1 paper, 2025). A malignant tumor arising from the epithelium that lines the cavity of the uterine body. "Validation in the GSE106191 (GPL570) dataset confirmed KLRG2 overexpression in endometrial carcinoma (W = 752.5, p = 0.021)." (PMID 40722666, 2025). "In summary, KLRG2 emerges as a linchpin of endometrial cancer progression, integrating proliferative signaling, epigenetic reprogramming, and immune microenvironment remodeling." (PMID 40722666, 2025).
endometrioid carcinoma (1 paper, 2025). "Subgroup analysis confirmed the prognostic significance of KLRG2 high expression in patients aged > 60 years, G3 tumors, endometrioid carcinoma, and FIGO III and IV disease." (PMID 40722666, 2025).
lung adenocarcinoma (1 paper, 2025). A carcinoma that arises from the lung and is characterized by the presence of malignant glandular epithelial cells. "Elevated KLRG2 in lung adenocarcinoma marks pyroptosis-related subtypes and adverse prognosis." (PMID 40722666, 2025).
prostate carcinoma (1 paper, 2021). A carcinoma that arises from epithelial cells of the prostate gland. "Genetic variation in KLRG2 may influence the aggressiveness of prostate cancer." (PMID 34026368, 2021).
cancer (2 papers, 2023 to 2025). A tumor composed of atypical neoplastic, often pleomorphic cells that invade other tissues. "While killer cell lectin-like receptor G2 (KLRG2) exhibits oncogenic properties in other cancers, its clinical significance and mechanistic roles in EC are unknown." (PMID 40722666, 2025). "While the roles of HSPD1 and KLRG2 play a role in regulating γδ T cell-mediated cytotoxicity in cancer have been described, there is limited information about the involvement of BTNL9 in γδ T cell-mediated killing of cancer cells." (PMID 38090581, 2023).
Tumor (2 papers, 2023 to 2025). "Analysis of the TIMER database revealed significant associations between KLRG2 expression and tumor immune microenvironment parameters in EC." (PMID 40722666, 2025). "This study aims to systematically characterize KLRG2 expression in EC, evaluate its prognostic significance, decipher underlying molecular mechanisms, and explore its role in tumor immune microenvironment regulation." (PMID 40722666, 2025). "This integrative multi-omics study establishes KLRG2 as a pivotal orchestrator of endometrial carcinogenesis, coordinating tumor-intrinsic proliferation, epigenetic reprogramming, and microenvironmental immunosuppression." (PMID 40722666, 2025). "The antagonism between KLRG2-driven oncogenesis and immune suppression underscores the need for combination therapies targeting both tumor-intrinsic pathways and extrinsic immune escape mechanisms." (PMID 40722666, 2025). "We evaluated the expression of KLRG2 using the Tumor Immune Single-cell Hub 2 (TISCH2) database, which focuses on the tumor microenvironment." (PMID 37974107, 2023). "Future single-cell analyses are warranted to dissect KLRG2-mediated tumor-immune crosstalk." (PMID 40722666, 2025). "KLRG2 expression demonstrated significant variations across FIGO stages, histologic subtypes, tumor grades, residual tumor status, and myometrial invasion depth (p < 0.05)." (PMID 40722666, 2025). "Killer cell lectin-like receptor subfamily G member 2 (KLRG2), a C-type lectin-like receptor, regulates tumor progression and immune responses." (PMID 40722666, 2025).
KLRG2 also shares sentences with these, for which no sentence is quoted: breast carcinoma (1 paper); cervical cancer (1); esophageal carcinoma (1); nodular sclerosis (1); ovarian carcinoma (1); testicular cancer (1).